KRAS (KRas proto-oncogene, GTPase)
Diseases named in the same sentence as KRAS in open-access papers (continued):
Sharing a sentence is not in itself a finding about the gene and the disease.
lung cancer (continued). "Subsequently, we stratified the LUAD patient samples based on the expression of these 16 TSGs and found that high expression of these genes is collectively predictive of positive outcomes in KRAS mutant lung cancer patients, but not in patients with KRAS wild-type tumors." (PMID 37407562, 2023). "In line with observations from human KRAS mutant cell lines, Cre-mediated in vitro knock-out of Uhrf1 in UKP cells decreased colony growth in 2D and 3D compared to the empty adenovirus control, further supporting a critical role for UHRF1 in KRAS-driven lung cancer." (PMID 37407562, 2023). "Furthermore, oncofetal CS expression was recently studied in lung cancer, and elevated levels were found to predict poor disease-free and overall survival in early-stage NSCLC independent of the presence of KRAS and EGFR mutations." (PMID 37108213, 2023). "Furthermore, recent research has shown that the KRAS mutant lung cancer growth is driven by heterodimerization of CRAF and ARAF, not merely by CRAF kinase activity." (PMID 38111008, 2023). "Importantly, CRISPR/Cas9-mediated knockout of NOP56 dramatically increased the sensitivity of KRAS-mutant (H358, H460) but not of wild-type (H520, H1703) lung cancer cells to rapamycin." (PMID 35039048, 2022). "Furthermore, clinical findings in patients with lung cancer given AMG510 and anti–PD-1/PD-L1 in combination (NCT03600883) indicate that KRAS G12C inhibition sensitizes the TME and enhances TIL infiltration into the tumor site, increasing the efficacy of immunotherapy." (PMID 35014625, 2022). "However, there is disappointing data from the phase III trial in which selumetinib+docetaxel in patients with advanced KRAS-mutant lung cancer did not improve overall survival." (PMID 36686779, 2022). "We use differences in patterns of Darwinian selection for critical genes in mutant EGFR (EGFR-mut), mutant KRAS (KRAS-mut), and non-EGFR/KRAS (NEK) lung cancers to identify variations in their evolutionary arcs and associated co-adaptations that govern their molecular characteristics." (PMID 36612014, 2022). "Until very recently, no drugs were available to treat mutant KRAS-driven lung cancer." (PMID 36074553, 2022). "In the old lung cancer group, there were genes significantly concurrent with actionable driver genes (CDKN2A, NF1): FAT1, LRP1B, ARID2 with CDKN2A; EPHB1 with NF1, and genes significantly exclusive with actionable driver genes (EGFR, KRAS): MLL2, STK11, KRAS with EGFR." (PMID 35096611, 2021). "However, patients with KRAS-mutant lung cancer are not sensitive to RTKi drugs; thus, an effective alternative treatment is urgently needed." (PMID 34635780, 2021). "Taken together, this study uncovers a role for KIMAT1 in maintaining a positive feedback loop that sustains KRAS signaling during lung cancer progression and provides a proof of principle that interfering with KIMAT1 could be a strategy to hamper KRAS-induced tumorigenesis." (PMID 33795683, 2021). "Mechanisms of macrophage recruitment in KRAS mutant lung cancer are not well defined, but it has been hypothesized a role for CXCR2 signaling." (PMID 33777798, 2021). "Also, RESV appear to reveal antiangiogenic activity in KRAS-mutant lung cancer, but not in EGFR mutant." (PMID 33652978, 2021). "The KRAS G12C inhibitor known as JNJ-74699157 is currently being tested in a phase I clinical trial to determine the tolerated dose in patients with advanced solid tumors, including lung cancer (Clinicaltrials.gov Identifier: NCT04006301 (accessed on 24 February 2021))." (PMID 33801965, 2021).
lung cancer (continued). "As with mouse KRAS G12D cells, stimulation of PERK autophosphorylation at T982 (p-PERK) by TG treatment was associated with increased p-eIF2α and p-ERK as well as decreased DUSP6 expression in human lung cancer cells with KRAS G12C (H23, H358) but not in cells with WT KRAS (H1299, H1703)." (PMID 34330898, 2021). "“Non-KRAS oncogene-driven lung cancer subtypes (e.g., ROS1, MET, BRAF, HER2, RET) is less well-studied, however, most of these other non-KRAS molecular subtypes (possibly apart from BRAF V600 mutation and MET gene alteration) are associated with a light-to-never smoking history." (PMID 34575691, 2021). "Oncogenic driver gene mutations, such as those in epidermal growth factor receptor (EGFR), KRAS, ALK, human epidermal growth factor receptor 2 (HER2), and mesenchymal-epithelial transition (MET), play essential roles in the initiation, progression, and clinical treatment of lung cancer." (PMID 34660325, 2021). "In addition, we have investigated the correlation between EZH2 expression and EGFR expression, KRAS expression, BRAF expression, and smoking in TCGA database to further explore the mechanism behind the influence of high EZH2 expression on lung cancer prognosis." (PMID 33299862, 2020). "Besides EGFR T790M, other resistance mutations can only be detected by the UltraSEEKTM Lung Panel (in BRAF, ERBB2, KRAS and PIK3CA, as well as EGFR C797S) and could be are useful for treatment decision making for lung cancer patients." (PMID 33081150, 2020). "Moreover, there is a relatively high percentage of AYAs with lung cancer who never smoked and have driver mutations, such as EGFR, ALK, KRAS, and ROS1." (PMID 33218178, 2020). "Almost half (48.4%) of our lung cancer patients had lung squamous cell carcinoma (SCC), which is often perceived to lack molecular targets, however our results suggest that KRAS, PIK3CA, PTPN11 and CDKN2A, in particular, could potentially be actionable targets in lung SCC." (PMID 32087721, 2020). "Moreover, Id1 silencing also resulted in significant increased levels of surface PD-L1 expression in the murine KRAS-driven lung cancer LLC, Lacun3 and 393 P cell lines, often even without the need for a pro-inflammatory stimulus (IFN-γ exposure in this case)." (PMID 33126649, 2020). "However, in contrast to our current study, the clinical utility of ADAM17 specifically in mutant KRAS LAC (which accounts for ~15% of all lung cancers) was not investigated." (PMID 30833304, 2019). "In other tumor types, such as melanoma, colorectal, and lung cancer, activating BRAF mutations occur mostly in a non-overlapping distribution with other genes that converge on activation of ERK signaling pathways (i.e., KRAS, NRAS, NF1, EGFR)." (PMID 31158244, 2019). "Intriguingly, lung cancer cell lines bearing KRAS mutation are more sensitive to KRA-533 than those without KRAS mutation, indicating KRA-533 may be relatively selective for mutant KRAS lung cancer cells." (PMID 30971271, 2019). "The prognostic role of KRAS in lung cancer is not consensual, with diverge reports." (PMID 30824880, 2019). "Increased copy number of mutant oncogenic KRAS that typically occurs later in the process of tumorigenesis further activates glycolytic metabolism and supports glutathione synthesis, but can also direct metabolites into the TCA cycle in lung cancer cells to support tumor progression." (PMID 31681559, 2019). "Our results provide a strong rationale for combining current chemo and anti-MEK cancer drugs with inhibitors of the HSP90/AXL/eIF4E/UPR pathway to treat KRAS-mutant lung cancer and perhaps other malignancies for which no effective therapy available for advanced diseases." (PMID 31431614, 2019).
lung cancer (continued). "Regarding KRAS oncogene, despite the fact that KRAS-MAPK pathway is downstream of EGFR signalling, KRAS-mutation-driven lung cancers, which are mostly adenocarcinomas, do not respond to EGFR TKIs because the mutations in KRAS activate and release mutant KRAS from the upstream regulation." (PMID 31795465, 2019). "KRAS has also been shown to be a negative prognostic marker for lung cancer." (PMID 29504894, 2018). "None of these factors have been studied in the human KRAS locus, although there is evidence that cis-acting elements, presumably located in introns or in 3’-untranslated regions decide the balance between KRAS-4A and KRAS-4B in murine lung cancer." (PMID 29755673, 2018). "Interestingly, chromosome 3 gain has not been observed in a BRCA1 driven murine breast cancer model, nor a KRAS driven model of non–small cell lung cancer while frequent partial gain of this chromosome was described in a MYC driven murine model of lymphoma." (PMID 29492199, 2018). "Similarly, in KRAS-mutant lung cancers, PFS (5.0 months, 95% CI 3.67–6.33) was inferior compared with EGFR-mutant (6.5 months, p = 0.242) and ALK/ROS1-rearranged (9.2 months, p = 0.007) lung cancers." (PMID 29587667, 2018). "The KRAS gene is mutated in approximately 20% of NSCLC cases, and the EGFR gene is defective in approximately 10% of NSCLC patients and in nearly 50% of non-smoker lung cancer cases." (PMID 29912931, 2018). "Moreover, we are not alone in identifying miR-29b as an oncogene in lung cancer as its expression has been shown to protect KRAS-transformed lung cells from apoptosis by inducing the NF-κB pathway." (PMID 29088821, 2017). "Honokiol-induced autophagy may perform a pro-death process in KRAS mutant lung cancer cells, but not pro-survival response, as autophagy inhibitor 3-MA was application reduced honokiol-mediated cytotoxicity." (PMID 28443025, 2017). "In agreement with those previous reports, we have demonstrated here a robust increase of IL-8 secretion and upregulation of CXCR1 in erlotinib-resistant lung cancer cells, compared to their parental counterparts, regardless of the mutational status of EGFR or KRAS." (PMID 27248176, 2016). "Unlike colon carcinoma, where tumors harboring mutant KRAS are known to be resistant to EGFR inhibition, the significance of KRAS mutations upon the benefit of anti-EGFR therapies in patients with lung cancer remains unclear." (PMID 27248176, 2016). "Among the nine variant-positive cases in the KRAS experiment, eight were EGFR mutation-negative lung cancers that had substitutions in codon 12, and one was an EGFR mutation-positive case in which the substitutions were non-synonymous and located outside of the hotspot region." (PMID 26126624, 2015). "Our results suggest that mesothelin targeted therapies could be useful in patients with KRAS mutant lung cancer, a subtype for which no targeted therapies are currently available." (PMID 26028668, 2015). "Of note, there was not a single patient in this trial with KRAS mutant advanced lung cancer." (PMID 26668062, 2015). "Last, advanced stage ALK-positive lung cancers may have a higher propensity for pleural and pericardial disease than lung cancers lacking ALK, KRAS, or EGFR mutations." (PMID 24955213, 2014). "Despite being the activator of RAS signalling pathway, EGFR derives less attention in this aspect due to activating mutations in KRAS, which are significantly associated with lack of response or resistance with some of the EGFR inhibitors like cetuximab in colorectal and lung cancers." (PMID 24147022, 2013). "They then correlated this KRAS lung cancer signature with gene expression profiles in human lung cancer studies and found that the mouse signature shared significant similarity with human lung adenocarcinoma but not with other lung cancer types." (PMID 19079768, 2007).
lung cancer (continued). "LKB1-deficient cell lines with high ΔAUC values exhibited robust apoptosis upon combined inhibition of KRAS/MAPK and MCL-1, while the apoptotic response of LKB1 wild-type (WT) cell lines was minimal, suggesting that LKB1 may modulate apoptotic dependencies of KRAS-mutant lung cancers." (PMID 40316540, 2025). "However, our study broadens this knowledge by analyzing two EGFR‐mutant cell lines, unlike most RKIP studies in lung cancer, which focus on KRAS‐mutant A549 cells, thus expanding the understanding of RKIP's relevance in EGFR‐mutant settings, which account for 10–30% of NSCLC cases." (PMID 40720248, 2025). "Thus, KRAS status could not be used as an indicator to predict the efficiency of chemotherapy in lung cancer." (PMID 37509464, 2023). "Cell proliferation defects in KRAS mutant pancreatic cancer cells in response to CRAF inhibition occur without p-ERK attenuation and may be attributed to the differences in the kinase-dependent and kinase-independent roles of CRAF in KRAS mutant lung cancer compared to KRAS mutant PDAC." (PMID 38111008, 2023). "Representatively, lung cancer harboring EGFR mutations is generally not considered for treatment with ICIs given that multiple clinical trials have found that ICIs provide limited survival benefit for this particular population, whereas KRAS mutation is a favorable biomarker for ICIs benefit." (PMID 36426352, 2022). "Compared with stage-IIIB/IV lung cancer patients with pan-negative driver mutations (OS 12.3 months), those with mutations of EGFR (OS 22.5 months) or ALK (OS 21.9 months) experienced better OS; while KRAS mutations (OS 6.4 months) were associated with poor OS." (PMID 35713442, 2022). "However, ARS-853 has not entered clinical evaluations in KRAS mutant lung cancer yet." (PMID 35004317, 2021). "Therefore, it may be concluded that RESV normalizes tumor angiogenesis in KRAS-mutant lung cancer but not in EGFR-mutant ones." (PMID 33652978, 2021). "Because IKKβ targeting in KRAS-induced lung cancer reduces tumour histological grade, angiogenesis and is required for activation of NF-κB, which, in turn, has been shown to be critical for TIC activity in different contexts, we hypothesised that IKKβ would be activated in KRAS-induced lung TICs." (PMID 32823550, 2020). "However, ARS-853 has not entered clinical evaluations in KRAS mutant lung cancer as yet." (PMID 32560574, 2020). "However, unlike KRAS, point mutations in RAC1 are rare in lung cancer." (PMID 32158759, 2020). "However, guidelines do not recommend use of KRAS testing in lung cancer." (PMID 29554880, 2018). "The model could be a useful tool in lung cancer research targeting KRAS and EGFR negative tumors." (PMID 29415661, 2018). "Thus, Src appears to exert mutant KRAS-driven events as its downstream effector, and considering our previous finding demonstrating the involvement of IGF1R activation in the development of lung cancer, co-targeting IGF1R and Src may halt the progression of mutant KRAS-driven lung tumor development." (PMID 29455661, 2018). "Notably, most of these studies address the role of ZEB1 by using cells or mouse models that express mutant KRAS, without exploring whether ZEB1 has different roles in lung cancer cells without KRAS mutations." (PMID 27456471, 2016). "As KRAS is still considered as an undruggable target and is responsible for 30% of all Caucasian AC cases, we investigated whether STAT3 inhibition has a potential survival benefit in a preclinical lung cancer mouse model and in a human cell line xenograft model." (PMID 25734337, 2015). "Consequently, further genetic and molecular studies using next-generation sequencing explored whether MPM involving lung cancer share common molecular targets, such as EGFR, Kirsten rat sarcoma viral oncogene homolog (KRAS) and anaplastic lymphoma kinase (ALK) to improve therapeutic outcome." (PMID 26466785, 2015).
lung cancer (continued). "They took 60 lung cancer samples from patients who had been treated with one of the drugs and either responded (that is, their tumors shrunk in size) or not, and tested whether the tumors had normal or abnormal KRAS." (PMID 15696205, 2005). "A reason for the lower driver mutation screening rates in patients with ILD and lung cancer could be that the preexisting ILD may be associated with the development of severe drug-induced pneumonitis in NSCLC patients treated with tyrosine kinase regimens, but this is not the case for the KRAS G12C." (PMID 39062713, 2024). "Among the seven studies, two reported advanced or recurrent KRAS-mutant NSCLC, three reported stage IV NSCLC, one reported stage IV adenocarcinoma, and one reported non-specified advanced lung cancer." (PMID 39090580, 2024). "In the murine models of KRAS-dependent lung cancer, WT1 deletion/suppression led to senescence only in KRAS-expressing cells, and did not impact wild-type cells, while WT1 loss determined reduction in tumor burden." (PMID 35453662, 2022). "The EZR-ROS1 fusion gene was specifically detected in lung cancer specimens of female never-smokers without EGFR, KRAS, and ALK alterations." (PMID 23418494, 2013). "Lung cancers were otherwise driver negative, and PDAC cases were KRAS wild type." (PMID 41390931, 2026). "Further analysis of the CANCERTOOL database revealed that the expression of FKBP10 was similar between lung adenocarcinoma bearing mutant KRAS, EGFR, and KRAS/EGFR non-mutants, suggesting that the relevance of FKBP10 in lung cancer is not limited to a specific genotype." (PMID 37201304, 2023). "KRAS is activated as a consequence of the phosphorylation of EGFR, however targeting ERBB RTK signaling using erlotinib and gefitinib showed no impact on disease progression in KRAS-mutant lung cancers." (PMID 36899885, 2023). "The EGFR wild type and KRAS mutant Lewis lung carcinoma (LLC1)-bearing mouse is widely used as a model for testing the molecular mechanisms, anti-metastatic activity, and immunity of anticancer agents, although it is not an EGFR-mutant lung cancer model." (PMID 36547898, 2022). "For example, the expression of GATA2 in human and mouse lung tumors were distinctly downregulated compared with normal lung tissues and its further suppression was not an effective treatment for KRAS mutant lung cancer 12, while GATA2 was essential for survival of KRAS mutant NSCLC cells." (PMID 34093794, 2021). "In human lung cancer cells, ISRIB acted in a dose-dependent manner to increase DUSP6 and decrease p-ERK in TG-treated H23 and H358 cells with KRAS G12C but not in H1299 and H1703 cells with WT KRAS." (PMID 34330898, 2021). "Further, miR-217 expression was significantly lower in lung cancer tissues than in noncancerous tissues, and enhanced miR-217 inhibited cell proliferation, migration, and invasion, while induced apoptosis of SPC-A-1 and A549 cells via targeting KRAS." (PMID 28219405, 2017). "Importantly, a large percent of lung cancer and CRC patients harboring wildtype KRAS, do not realize benefit from EGFR-targeted agents." (PMID 19439077, 2009).